BTLA (B and T lymphocyte associated)
Diseases named in the same sentence as BTLA in open-access papers (continued):
Sharing a sentence is not in itself a finding about the gene and the disease.
diffuse large B-cell lymphoma (10 papers, 2020 to 2025). "High HVEM and low BTLA mRNA levels in tumor cells from patients with follicular lymphoma (FL) and diffuse large B-cell lymphoma (DLBCL) were associated with shorter time-to-treatment, overall survival, and increased risk of transformation from FL to DLBCL." (PMID 37649037, 2023). "For instance, the presence of BTLA + T cells in the tumor microenvironment was associated with lower cytotoxic capability, advanced stage, and poor prognosis in diffuse large B-cell lymphoma." (PMID 37041226, 2023). "Similarly, upregulated expression of BTLA on CD8+ or CD4+ T cells or increased levels of soluble BTLA were associated with unfavorable prognosis for gallbladder cancer, diffuse large-B cell lymphoma, clear cell renal cell cancer, and prostate cancer patients." (PMID 34208480, 2021). "High expression of BTLA in T cells was correlated with advanced-stage diffuse large B-cell lymphoma." (PMID 40463377, 2025). "In diffuse large B cell lymphoma (DLBCL) and follicular lymphoma, BTLA expression on T cells and B cells has also been associated with aggressive molecular subtypes and reduced event-free survival." (PMID 41471273, 2025). "In hematological malignancies, BTLA/HVEM axis dysregulation has been linked to T cell functional exhaustion and poor prognosis in diffuse large B cell lymphoma (DLBCL) and follicular lymphoma (FL)." (PMID 33917094, 2021). "BTLA expression has also been reported in diffuse large B cell lymphoma (DLBCL) and follicular lymphoma, primarily on intratumoral T cells and B cells, with emerging data indicating that BTLA may predict therapeutic resistance or unfavorable immune subtypes." (PMID 41471273, 2025). "Indeed, in patients with diffuse large B cell lymphoma, BTLA+ T cells from the tumor microenvironment exhibit less cytolytic activity than their BTLA‐deficient counterparts." (PMID 32508018, 2020). "Other B-cell NHLs, including mantle cell lymphoma (MCL), follicular lymphoma (FL), diffuse large B-cell lymphoma (DLBCL), marginal zone lymphoma (MZL), and Burkitt lymphoma (BL), showed no or a weak BTLA signal." (PMID 38233898, 2024).
glioma (10 papers, 2017 to 2025). A benign or malignant brain and spinal cord tumor that arises from glial cells (astrocytes, oligodendrocytes, ependymal cells). "For instance, B7‐H3, TIM3 and LAG3 were more likely to associate with the occurrence of glioma, while B7‐H3, TIM3, BTLA, PD‐1, and PD‐L1 were more likely to associate with the development of glioma via immunosuppression." (PMID 35668574, 2023). "Studies have shown that the immune checkpoint ligands ICOS, BTLA, TNFRSF1A, and TNFRSF1B all contribute to glioma immune evasion." (PMID 36882457, 2023). "Our study found that several immune checkpoints (BTLA, CD200R1, PD-L1, B7-H3, CD70, CTLA4, IDO1, and PD1) in patients with CDC42 high expression glioma were upregulated compared to the CDC42 low expression group." (PMID 37476838, 2023). "Specifically, we found that, as IGFBP5 levels increased, the expression of the seven immune checkpoint genes (BTLA, CD274, CTLA4, HAVCR2, LAG3, PDCD1, and PDCD1LG2) were increased and a large positive correlation was observed between IGFBP5 and these immune checkpoints in glioma." (PMID 38164271, 2024). "We found that in patients with glioma, B7‐H3, LAG3 and TIM3 were significantly raised, while the expression of PD‐L1, BTLA, TIGIT, PD‐1 and CTLA4 did not seem to be significantly different from those of normal individuals." (PMID 35668574, 2023). "Other immune checkpoint molecules, including lymphocyte activation gene-3 (LAG-3; also known as CD223), 2B4 (also known as CD244), B and T lymphocyte attenuator (BTLA; also known as CD272), have not been fully explored for their biological activities and functions in glioma." (PMID 27756892, 2017).
renal cell carcinoma (10 papers, 2019 to 2025). "In our previous studies, we showed a significant association between BTLA gene variants and susceptibility to chronic lymphoblastic leukemia and renal cell carcinoma in the Polish population." (PMID 36741370, 2022). "So far, it has been demonstrated that expression of serine/arginine-rich splicing factor 2 (SRSF2) in renal cell carcinoma patients (RCC) is involved in the regulation of IC expression (inter alia BTLA), which in turn modulates TILs’ exhaustion." (PMID 38233898, 2024). "BTLA rs1982809 polymorphism, a 3′-UTR SNP, was found to be associated with the development of renal cell carcinoma in Polish populations." (PMID 31774112, 2019). "BTLA gene variations have been connected with the risk of cancer development in a few previous studies including our recent studies on CLL and renal cell carcinoma (RCC)." (PMID 36741370, 2022). "HVEM is a ligand of B- and T-lymphocyte attenuator (BTLA) and soluble BTLA in combination with sTIM-3 may be able to predict the rates of disease recurrence and survival among renal cell cancer patients." (PMID 32722224, 2020). "In Polish population, it was found that BTLA rs1982809 G>A, a 3′-UTR SNP, might be a low-penetrating risk factor for the development of renal cell carcinoma." (PMID 31774112, 2019).
viral infection (10 papers, 2012 to 2024). "We also found increased expression of other co-inhibitory molecules (BTLA, FASLG, FAS, and IDO1) that are associated with the regulation of T-cell exhaustion during chronic viral infection." (PMID 32731586, 2020). "The differential BTLA expression may reflect the immune response to the instigating pathogen, where a viral infection like SARS-CoV-2 requires a greater T-cell response." (PMID 38632526, 2024). "Recent studies on M. tb infection have found that, in comparison with HC, ATB patients exhibited enhanced expression of BTLA on myeloid and plasmacytoid dendritic cells (DCs) from peripheral blood and TPE, different from the high level of BTLA expression on T cells observed in virus infection." (PMID 35701741, 2022). "The present study revealed that BTLA functions not only as an inhibitory receptor, BTLA could also, in the context of a live virus infection, serve as a trans-activating ligand for HVEM." (PMID 24205056, 2013). "It is possible that during natural bacteria or viral infections in Light−/− mice, BTLA and/or CD160 may signal through HVEM to compensate for the absence of LIGHT." (PMID 24205057, 2013). "Positive expression of iRs such as PD1, CTLA-4, TIM3, LAG-3, 2B4, CD160, and BTLA has been directly linked to reduced cytokine production by T cells from cancer patients (including reports from our group) or in the chronic LCMV mouse model of “T cell exhaustion” and other viral infections." (PMID 24391639, 2013).
esophageal squamous cell carcinoma (9 papers, 2020 to 2025). Esophageal squamous cell carcinoma (ESCC) is a type of esophageal carcinoma (EC) that can affect any part of the esophagus, but is usually located in the upper or middle third. "This study aimed to evaluate whether BTLA variants were related to the risk of esophageal squamous cell carcinoma (ESCC)." (PMID 32060969, 2020). "In another study, we found that the BTLA rs3112270 A>G and rs2171513 G>A polymorphisms could modify the risk of esophageal squamous cell carcinoma (ESCC)." (PMID 33564688, 2021). "did not observe any significant relationship between BTLA polymorphisms and esophageal squamous cell carcinoma." (PMID 36741370, 2022).
malaria (7 papers, 2013 to 2021). Malaria is a serious and sometimes fatal disease caused by a parasite that commonly infects a certain type of mosquito which feeds on humans. "BTLA suppresses both the innate and T/B cell-dependent adaptive immune responses during experimental malaria, whereas BTLA-/- mice show markedly decreased parasitemia, and early clearance of infections." (PMID 33859648, 2021). "We have shown and so have others that the co-inhibitory receptors PD-1, CTLA4 and BTLA are induced during malaria." (PMID 30483269, 2018). "Thus, BTLA-HVEM interaction is relevant to malaria but while blockade would be beneficial to controlling parasitemia, it could increase the incidence of cerebral malaria." (PMID 30631323, 2018). "Thus, indicating that both BTLA and LIGHT are important immune regulators during experimental malaria." (PMID 30631323, 2018).
nosocomial infection (7 papers, 2013 to 2025). An infection acquired in a hospital or other healthcare setting. "Moreover, the non-septic patients with CD4+ T-cells that were greater than 80% BTLA+ were more susceptible to developing nosocomial infections." (PMID 24289156, 2013). "Additionally, BTLA expression contributed to primary and secondary lymphoid organ apoptotic cell loss in experimentally septic mice; thus, BTLA-induced apoptotic lymphocyte loss may be a mechanism for increased nosocomial infection risk in critically ill patients." (PMID 24289156, 2013). "An increased BTLA+ CD4+ lymphocyte frequency in the observed critically ill non-septic patients was associated with a subsequent infection; therefore, BTLA may act as a biomarker to help determine nosocomial infection development." (PMID 24289156, 2013).
B cell lymphoma (6 papers, 2018 to 2024). "Mutations affecting the binding site of HVEM interaction with BTLA in cis promotes B cell lymphoma development because of unleashed BCR signaling and dysregulation of B cell activation and further differentiation." (PMID 37033927, 2023). "In B-cell lymphoma from germinal center, loss-of-function mutations in HVEM and the disrupted interaction between this receptor and BTLA stimulates the proliferation of malignant B cells; thus, in this case, BTLA is a tumor suppressor." (PMID 33114418, 2020). "B cell lymphoma-derived exosomes upregulated inhibitory receptors PD-1 (programmed cell death protein 1), CTLA-4 (cytotoxic T lymphocyte-associated antigen-4) and BTLA (B- and T-lymphocyte attenuator), and induced apoptosis of T cells through activation of Fas/Fas ligand pathway." (PMID 37182123, 2023). "Moreover, they showed BTLA expression in CLL/small lymphocytic lymphoma (B-CLL/SLL), but not in other B cell lymphomas including follicular lymphoma, mantle cell lymphoma, and marginal zone lymphoma." (PMID 32775467, 2020).
clear cell renal cell cancer (6 papers, 2021 to 2025). "BTLA expression was increased in T cells in multiple cancers, and sBTLA was found to be associated with poor survival in clear-cell renal cell cancer and pancreatic cancer." (PMID 38730580, 2024). "In addition, soluble BTLA (sBTLA) in plasma is significantly associated with the risk of death in patients with clear cell renal cell cancer, suggesting that sBTLA has a similar role to membranous BTLA in inhibiting T cell response." (PMID 33859648, 2021). "Increased levels of soluble BTLA have been found to correlate with lower survival rates in patients with clear renal cell carcinoma and patients with advanced hepatocellular carcinoma." (PMID 34722568, 2021). "High blood levels of BTLA and TIM3 correlated with decreased survival in clear-cell renal cell carcinoma." (PMID 38730580, 2024).
dermatitis (6 papers, 2015 to 2025). An inflammatory process affecting the skin. "BTLA-deficient mice thus exhibit enhanced disease in a γδ T cell-dependent model of dermatitis whereas an agonistic BTLA antibody reduces inflammation." (PMID 26347741, 2015). "Additionally, BTLA can increase the number and activity of γδT cells and reduce the symptoms of skin inflammation; Btla−/− mice have a reduced number of γδT cells and are susceptible to dermatitis." (PMID 30984188, 2019). "Moreover, BTLA expression was recently shown to block γδ T cell cytokine production and to limit γδ T cell-dependent dermatitis." (PMID 29518903, 2018). "Consequently, BTLA-deficient mice accumulated IL-17+ CD27− γδ T-cells and were more susceptible (than wild-type controls) to dermatitis, which could be reversed by agonist BTLA antibodies." (PMID 25674089, 2015). "Related to dermatitis, we found an upregulation of CD74, BTLA, TRAF2, TNIP1, and IL19." (PMID 41416938, 2025).
lung adenocarcinoma (6 papers, 2019 to 2025). A carcinoma that arises from the lung and is characterized by the presence of malignant glandular epithelial cells. "In lung adenocarcinoma, Lou et alfound that multiple immune checkpoints associating with increased regulatory T cells including PD-L1, PD-1, TIM-3, B7-H3, BTLA and CTLA-4 displayed EMT phenotype." (PMID 36467998, 2022). "In a lung adenocarcinoma TMA, protein expression of immune checkpoint molecules (A2A, BTLA, CTLA4, INOS, TIM3, and PDL1) did not correlate with MFS or overall survival." (PMID 30783512, 2019).
lymph node metastasis (6 papers, 2020 to 2025). "High BTLA levels were found in 37.5% of all BTLA-positive patients and associated with lymph node metastasis as well as negatively correlated with patient survival." (PMID 38233898, 2024). "In addition, the HVEM and BTLA expression was linked to poorer overall survival and characteristics of tumor progression such as the depth of invasion, lymph node metastasis, and the histological grade." (PMID 40243455, 2025). "High expression of BTLA was significantly associated with lymph node metastasis and poor prognosis." (PMID 36387235, 2022). "Low BTLA expression was associated with less lymph node metastasis (p = 0.0123)." (PMID 32793631, 2020). "Interestingly, elevated BTLA levels were found to be associated with lymph node metastasis." (PMID 38233898, 2024). "CRC samples with qualified clinical information were analyzed using the Chi-Squared test, hence revealing that higher expression of BTLA significantly correlated with the lower grade of lymph node metastasis." (PMID 32793631, 2020). "Additionally, BTLA levels were significantly higher in patients with lymph node metastasis and advanced disease." (PMID 38233898, 2024). "The Chi-Squared test revealed that BTLA expression was correlated to lymph node metastasis." (PMID 32793631, 2020).
non-small cell lung carcinoma (6 papers, 2021 to 2025). A group of at least three distinct histological types of lung cancer, including non-small cell squamous cell carcinoma, adenocarcinoma, and large cell carcinoma. "In non-small cell lung cancer (NSCLC), BTLA expression is enriched in exhausted CD8+ T cells and correlates with reduced effector function and increased tumor burden." (PMID 41471273, 2025). "The EMT phenotype is positively correlated with PD-L1, PD-L2, PD-1, TIM-3, B7-H3, BTLA, and CTLA-4 expression, as well as CD4+ Foxp3+ Tregs expansion in non-small cell lung cancer (NSCLC)." (PMID 37152039, 2023). "FXR-HVEM axis serves as an immune evasion mechanism in PD-L1low/negative non-small cell lung cancer, which can be targeted by HVEM/BTLA blockade to evoke antitumor immunity." (PMID 40985894, 2025).
pancreatic cancer (6 papers, 2021 to 2024). "It has been shown that BTLA can be considered as a prognostic marker for pancreatic cancer." (PMID 35145483, 2021). "However, the functional inhibition of CCR7 and BTLA may be a key trigger for pancreatic cancer prevention." (PMID 34948416, 2021). "Our results suggest that Fx suppresses the CCL21/CCR7 axis downstream of Rho signaling, BTLA, TME, EMT, and adhesion in pancreatic tumors in mice." (PMID 34948416, 2021).
cervical cancer (5 papers, 2022 to 2025). A primary or metastatic malignant neoplasm involving the cervix. "The expression of BTLA, KLRK1, CD80, and CD28 reduced the risk score, and these were suggested as protective factors in cervical cancer prognosis." (PMID 39312339, 2024). "Blockade of BTLA and CD96 is promising for use in combination with PD1 blockade in the treatment of cervical cancer, as targeting the ICI CD96 overcomes PD1 blockade resistance by boosting CD8+ T-cell function." (PMID 38928307, 2024). "In cervical cancer patients, we found CSCC cohorts obtained higher TMB score, MSI score and common inhibitory checkpoints expression (e.g., PDCD1, CD274, BTLA, CTLA4, TIGIT, etc.), accompanied by more abundant immunocytes infiltration." (PMID 38206304, 2024).
colitis (5 papers, 2013 to 2025). Inflammation of the colon. "HVEM-deficient T cells (donors) or HVEM-/- hosts; also BTLA-/- mice in DSS colitis." (PMID 41030453, 2025). "In the adoptive T cell transfer colitis model, Tregs from HVEM-deficient mice showed impaired ability to suppress effector T cells, while BTLA-deficient effector T cells were resistant to Treg-mediated suppression when transferred into RAG-deficient hosts." (PMID 41030453, 2025). "The BTLA+ T cell frequency is elevated in the mucosa and blood of mice with colitis, and BTLA can control inflammatory responses by upregulating Foxp3 expression." (PMID 33859648, 2021). "By contrast, in GVHD and certain colitis models HVEM serves as an activating ligand to deliver pro-survival BTLA co-signals." (PMID 24205056, 2013). "In one example, studies in patients with microscopic colitis show altered immune checkpoint profiles, including varied expression levels of HVEM and BTLA in colon biopsies." (PMID 41030453, 2025). "BTLA recently has been reported to play a role in promoting the survival of activated T cells in mouse models of graft versus host disease (GVHD), and effector T cells during development of colitis in the CD4+CD45RBhigh T cell transfer model." (PMID 24205057, 2013). "Similarly in a CD4 T cell transfer model of colitis, BTLA−/− T cells transferred into Rag−/− hosts failed to accumulate, with the reduced number of effector T cells in the recipients ultimately affecting disease progression." (PMID 24205056, 2013). "Other data showed that lack of BTLA reduced rather than augmented pathology in a colitis model and promoted survival of antigen-specific CD8+ T cells induced by bacterial infection again suggesting that BTLA may have disparate role in maintaining homeostasis of the immune system." (PMID 26277622, 2015).
gallbladder cancer (5 papers, 2020 to 2024). "Upregulated BTLA expression in gallbladder cancer (GBC) plays a role in inhibiting anticancer immunity, and an increased proportion of BTLA+CD8+ cells is related to the unfavorable outcome of GBC patients." (PMID 33859648, 2021).
graft versus host disease (5 papers, 2013 to 2023). An immune system disorder that occurs after allogeneic hematopoietic stem cell transplant and is a reaction of donor immune cells against host tissues. "Despite previous observations that classified BTLA as an inhibitory immune checkpoint, studies using BTLA−/− graft-versus-host disease (GvHD) mouse models demonstrated that it also plays an important role in favoring T lymphocyte survival." (PMID 37649037, 2023). "BTLA can inhibit donor anti-host T cell responses and ameliorate graft-versus-host disease (GVHD) resulting from allogeneic bone marrow transplantation." (PMID 33859648, 2021). "Treatment with an agonistic anti-BTLA antibody was found by Albring and colleagues to prevent graft-versus-host disease." (PMID 26329820, 2015). "Administration of agonistic anti-BTLA antibody has been shown to prevent graft-versus-host disease." (PMID 26329820, 2015).
Hepatitis (5 papers, 2013 to 2021). Inflammation of the liver. "When BTLA−/−NKT and NKT cells were purified in vitro and injected into the NKT−/− mice, mice receiving BTLA−/−NKT cells were more susceptible to Con A-induced hepatitis, indicating that BTLA inhibits hepatitis induced by NKT cells." (PMID 30984188, 2019). "Thus far, it has only been examined in ConA-induced hepatitis with both studies demonstrating that BTLA knockout increases iNKT cell cytokine production and exacerbates hepatitis, indicating an inhibitory role of BTLA in iNKT cell function." (PMID 29163518, 2017).